TPM3 (tropomyosin 3)
Diseases named in the same sentence as TPM3 in open-access papers (continued):
Sharing a sentence is not in itself a finding about the gene and the disease.
ovarian carcinoma (2 papers, 2013 to 2019). A malignant neoplasm originating from the surface ovarian epithelium. "Although each alteration is infrequent, ROS1 fusions with many kinds of 5′ partner genes (CCDC6, CD74, EZR, KDELR2, LRIG3, SDC4, SLC34A2 and TPM3) have been reported in lung, brain, biliary tract, and ovarian cancers." (PMID 23418494, 2013).
prostate carcinoma (2 papers, 2022 to 2024). A carcinoma that arises from epithelial cells of the prostate gland. "In this study, MSMB was one of only two proteins (including TPM3) to significantly associate and colocalise with all three prostate cancer outcomes." (PMID 38878676, 2024).
scoliosis (2 papers, 2020 to 2021). A congenital or acquired spinal deformity characterized by lateral curvature of the spine. "The E173A mutation in position 173 of γ-tropomyosin (Tpm3.12), encoded by the TPM3 gene, was detected in a 7-year-old boy with hypotonia, feeding difficulties, motor delay and scoliosis, requiring non-invasive ventilation while ambulant." (PMID 32580284, 2020). "One of these mutations, R90P in Tpm3.12, encoded by the TPM3 gene, was detected with hypotonia, feeding difficulties, motor delay, and scoliosis, requiring non-invasive ventilation while ambulant." (PMID 34204776, 2021).
Stroke (2 papers, 2012 to 2025). Sudden impairment of blood flow to a part of the brain due to occlusion or rupture of an artery to the brain. "In this respect the young rats had more genes encoding neuroprotective factors (Fgf9, Nr4a1, Tpm3) that had recovered by day14 post-stroke suggesting a better control of adult brain plasticity in young animals." (PMID 23251410, 2012).
T-cell lymphoma (2 papers, 2018 to 2019). "In contrast, ALK+ALCL, a kind of T-cell lymphoma, typically involves the NPM1-ALK or TPM3-ALK fusion gene." (PMID 29747676, 2018).
adenoma (1 paper, 2019). A neoplasm arising from the epithelium. "Biomarker levels were analyzed in plasma samples from healthy individuals, individuals with adenomas, CRC patients, and patients with non-cancer diseases and we identified one protein, tropomyosin 3 (Tpm3) that could discriminate CRC at a significant level (p = 0.0146)." (PMID 31810358, 2019).
Behcet disease (1 paper, 2016). A chronic, relapsing, multisystemic vasculitis characterized by mucocutaneous lesions, as well as articular, vascular, ocular and central nervous system manifestations. "Only three genes were found in common for both Dex and TAA: Myh8, Tpm3, identified as self-antigen in patients with Behcet's disease with posterior uveitis, and Elov1, with a role in fatty acid biosynthesis." (PMID 27429799, 2016).
Bloom syndrome (1 paper, 2025). Bloom syndrome (BSyn) is a rare chromosomal breakage syndrome characterized by a marked genetic instability associated with pre- and postnatal growth retardation, facial sun-sensitive telangiectatic erythema, increased susceptibility to infections, and predisposition to cancer. "The TPM3-NTRK fusion has been reported in a case of a child with Bloom syndrome, with the fusion appearing in both BLM alleles." (PMID 40151290, 2025).
brain tumour (1 paper, 2024). "During this procedure, SNUH utilized NGS with a brain tumour-targeted gene panel, identifying the TPM3::NTRK1 fusion, amplification of MDM4/AKT3, and one-copy loss of PTEN/FGFR2, leading to the diagnosis of the tumour as HGG, not otherwise specified (NOS), according to the WHO2021 criteria." (PMID 39014476, 2024).
clear cell renal cell carcinoma (1 paper, 2025). "Here, we show that the novel protein TPM3P9, encoded by the lncRNA tropomyosin 3 pseudogene 9, exhibits oncogenic activity in clear cell renal cell carcinoma (ccRCC) by enhancing oncogenic RNA splicing." (PMID 39865075, 2025).
colorectal tumor (1 paper, 2017). "We originally reported the identification of a chromosomal rearrangement involving NTRK1 (encoding the TRKA protein) and the TPM3 gene in the KM12 colorectal tumor cell line and showed for the first time that the resulting TPM3-TRKA fusion protein is an oncogenic driver sensitive to TRKA inhibitors." (PMID 28903424, 2017).
diabetes mellitus (1 paper, 2020). A metabolic disorder characterized by abnormally high blood sugar levels due to diminished production of insulin or insulin resistance/desensitization. "The results of this research may help explain the induction of tacrolimus-induced posttransplantation diabetes mellitus via the low expression of muscle genes including Tpm3, Tnnc1, Tnnt1, Tnni3, Hrh3, Apln, S1pr3, and Cxcl12." (PMID 31998808, 2020).
endometrioid tumor (1 paper, 2012). A benign, borderline, or malignant epithelial tumor of the female reproductive system characterized by the presence of glands and/or cysts lined by neoplastic cells that resemble endometrial cells.
heart failure (1 paper, 2026). Inability of the heart to pump blood at an adequate rate to meet tissue metabolic requirements. "Focusing on tropomyosin, we observed that while the predominant cardiac gene TPM1 showed moderate up-regulation of its transcript isoforms, transcripts derived from TPM3-typically expressed at lower levels in the healthy heart-were markedly increased in heart failure." (PMID 41530494, 2026).
Histiocytosis (1 paper, 2025). An excessive number of histiocytes (tissue macrophages). "KIF5B has been shown to be the most common fusion-partner gene in ALK-positive histiocytosis, whereas CLTC, TPM3, EML4, and TFG have only been infrequently recorded." (PMID 40700600, 2025).
Hypertension (1 paper, 2023). The presence of chronic increased pressure in the systemic arterial system. "Mechanistically, Alivec binds tropomyosin 3 (Tpm3) and heterogeneous nuclear ribonucleoprotein A2/B1 (Hnrnpa2b1) to regulate chondrogenic transformation of VSMCs implicated in vascular dysfunction and hypertension." (PMID 36672953, 2023).
ischemic heart disease (1 paper, 2024). "In conclusion, our findings highlight the therapeutic potential of TPM3 modulation in mitigating hypoxia-associated cardiac injury, suggesting a promising avenue for the treatment of ischemic heart disease and other hypoxia-related cardiac pathologies." (PMID 38928503, 2024).
leukemia (1 paper, 2023). A malignant (clonal) hematologic disorder, involving hematopoietic stem cells and characterized by the presence of primitive or atypical myeloid or lymphoid cells in the bone marrow and the blood. "Similarly, TPM3 accelerated leukemia via fusion with PDGFRB." (PMID 36639822, 2023).
mesenchymal neoplasms (1 paper, 2021). "To date, most of the fusions described in mesenchymal neoplasms involve NTRK1 and NTRK3 genes and include different fusion partner genes, most common being ETV6, LMNA, and TPM3." (PMID 32860002, 2021).
metastatic cancer (1 paper, 2019). A carcinoma which has spread from the original site of growth to another anatomic site. "Multiple lines of evidence of this study indicated that TPM3 mRNA was significantly increased in patients with metastatic cancer and could be delivered into cancer cells by microvesicles to promote the invasion of BC cells." (PMID 31705785, 2019).
nasopharyngeal carcinoma (1 paper, 2021). A carcinoma arising from the nasopharyngeal epithelium. "In nasopharyngeal carcinoma, circARHGAP12 is significantly upregulated and regulates the expression of cytoskeletal remodeling-related proteins (EZR, TPM3, and RhoA) through directly binding the mRNA 3′-UTR and promoting its stability via EZR/TPM3/RhoA complex." (PMID 34392306, 2021).
pleomorphic xanthoastrocytoma (1 paper, 2026). A WHO grade ll astrocytic tumor with a relatively favorable prognosis. "In the same study, a case of PA bore a fusion of breakpoint cluster region (BCR) and NTRK2 genes (BCR-NTRK2), while a patient with pleomorphic xanthoastrocytoma (PXA) harbored the tropomyosin 3 (TPM3)-NTRK1 fusion." (PMID 41514664, 2026).
renal cell carcinoma (1 paper, 2025). "The TPM3‐ALK fusion has been associated with a range of malignancies including IMTs, renal cell carcinoma (RCC), and other neoplasms." (PMID 41275415, 2025).
rigid spine syndrome (1 paper, 2021). "Putative causative mutations were found in the DES (two cases), CRYAB, TPM3, and SELENON (four cases) genes, the latter typically presenting with a rigid spine syndrome." (PMID 33652732, 2021).
sarcopenia (1 paper, 2025). Progressive decline in muscle mass due to aging which results in decreased functional capacity of muscles. "In this context, mitochondrial dysfunction–related genes such as SLC44A2, TPM3, PIPOX, and DHDPSL, which are represented among the 20 CpGs identified in our study, may play a contributory role in the pathophysiology of sarcopenia." (PMID 41297061, 2025).
Sepsis (1 paper, 2019). Sepsis is defined as life-threatening organ dysfunction caused by a dysregulated host response to infection. "Tpm1, Tpm2, and Tpm3 mRNA levels decreased in the TA after 24 and 48 h of sepsis." (PMID 31660704, 2019). "Tpm1, Tpm2, and Tpm3 mRNA levels decreased in the DIA after 48 h of sepsis." (PMID 31660704, 2019).
spinal cord tumour (1 paper, 2024). "A spinal cord tumour with the TPM3::NTRK1 fusion (patient #8, 2y/F) also exhibited a GBM-like pathology with MVP and necrosis." (PMID 39014476, 2024).
Spitz nevi (1 paper, 2024). "Two compound Spitz nevi (ALK1 and ALK2) demonstrated ALK fusions (TPM3-ALK rearrangement for both lesions) and showed characteristic histomorphology for this category of tumor, i.e., fascicles of spindled melanocytes with plexiform growth pattern, in addition to a dome-shape clinical appearance." (PMID 38791877, 2024).
tongue tumor (1 paper, 2018). "The present study identified cofilins (CFL1 and CFL2) and tropomyosin family proteins (TPM3 and TPM4) are significantly upregulated, in contrast, myosin family proteins (MYL2, MYL4 and MYLPF) were downregulated in tongue tumor samples as compared to normal samples." (PMID 29371635, 2018).
uterine sarcomas (1 paper, 2024). "In NTRK-rearranged uterine sarcomas, NTRK1 is more frequently involved in gene fusions than NTRK3, and TPM3::NTRK1 fusion is the most common translocation reported." (PMID 38151535, 2024).
tumor (44 papers, 2000 to 2025). "This review examines the molecular mechanisms underlying TPM3 fusions, the associated tumor types, and the therapeutic implications of targeting these alterations." (PMID 41275415, 2025). "The downregulation of miR-377-5p, which targets TPM3, exacerbates tumor malignancy, making TPM3 a promising diagnostic and therapeutic target." (PMID 41315466, 2025). "This review elucidates the molecular mechanisms underpinning TPM3 gene fusions, delineates the tumor types associated with these fusions, and examines their clinical implications." (PMID 41275415, 2025). "FBXO5 promotes similar pro-tumor events to those exerted by TPM3, making it another candidate as a dual diagnostic and prognostic biomarker." (PMID 40650278, 2025). "Similar to other tumor types, TPM3::NTRK1, EML4::NTRK3 and ETV6::NTRK3 fusion variants represented the majority of NTRK1–3 translocations identified in this study." (PMID 37686416, 2023). "Recent studies have identified and begun to elucidate the role of the TPM3‐ALK fusion gene in various rare tumor types beyond its well‐established associations, shedding light on its significance in diverse tumorigenesis contexts and its emerging potential as a diagnostic marker." (PMID 41275415, 2025). "Another protein proposed as a diagnostic and prognostic biomarker is tropomyosin 3 (TPM3), which is overexpressed in tumor tissue from CC patients compared to healthy tissue." (PMID 40650278, 2025). "Downregulation of CORO1C/TPM3 signaling also contributed to the inhibition of EC tumor metastasis in vivo." (PMID 38540273, 2024). "Three of the fusion partners among adults with CRC harboring an NTRK gene fusion tumor have been commonly reported in the literature, including TPM3::NTRK1, TPR::NTRK1, and LMNA::NTRK1." (PMID 38967220, 2024). "The expression of PF-4 and TPM3 was increased in cancer patients as compared to control individuals in the tumor tissue of the group of patients with comorbidities." (PMID 37176055, 2023). "The anti-TPM3 compound ATM-3507 described in the part of the introduction was shown to inhibit tumor growth by targeting the C-terminus of Tpm3.1." (PMID 37686101, 2023). "In the luminal A subtype, the variation in mRNA levels and overexpression of the VEGF, PDGF, ANG1, PF4, WASF3, and TPM3 genes coincided in both types of samples (platelets and tumor tissue, respectively)." (PMID 37176055, 2023). "Part of the reason why TPM3 is considered an oncogene is that its abnormal expression drives changes in other genes that allow tumor tissues to progress." (PMID 37686101, 2023). "TPM3 is a cell motility-related protein that is upregulated in a variety of tumor tissues and promotes tumor cell migration and invasion." (PMID 35287546, 2022). "Pz-1 inhibitory effect had a shorter duration in TPM3-TRKA tumours; thus, TRKA phosphorylation was fully restored after 8 h of treatment with 0.3 mg/Kg Pz-1, and after 12 h of treatment with 1 and 3 mg/Kg when it returned to levels even higher than baseline." (PMID 34373541, 2021). "In tumor samples, both stromal cells (yellow arrows) and tumor cells (black arrows) can express Tpm3 at different levels." (PMID 31810358, 2019). "We also identified a tumour with TPM3–ALK fusion, a second RCC case with this specific fusion reported in adults." (PMID 27713405, 2016). "A forest plot highlighted key oncogenic factors such as SNX5, YBX1, TPM3, and RAB7A, which were significantly associated with poorer survival and may drive tumor progression." (PMID 41031219, 2025). "Malignancies harboring TPM3 fusions encompass several tumor categories." (PMID 41275415, 2025). "Their results showed that TPM3‐ALK fusion protein is essential for tumor growth and maintenance." (PMID 41275415, 2025). "TPM3 is highly expressed in CC and plays a dual role in promoting tumor progression." (PMID 41315466, 2025). "Moreover, in tumor tissue from patients with comorbidities, there was an increase in the gene expression of TPM3 and PF4." (PMID 37176055, 2023).
tumor (continued). "Numerous studies have shown that TPM3 promotes tumor cell metastasis." (PMID 37370118, 2023). "TPM3, CHMP4C, EEF1A1, FASN, TNF, S100A10, and IL1A represent a high-risk score and poor prognosis, suggesting that these genes may be associated with the tumor process in patients with CC and appear to be pro-oncogenes." (PMID 36685937, 2022). "TPM3-TRKA G595R tumour growth remained unaffected by Pz-1 at all the doses." (PMID 34373541, 2021). "The increased presence of Tpm3 in the sera of patients bearing CRC samples could then be the result of increased expression of Tpm3 in tumor cells, a reflection of invasion of tumor cells through the lamina muscularis mucosae, or a combination of both." (PMID 31810358, 2019). "Consistent with previous studies, we found the exogenous TPM3 delivered by platelet‐releasing microvesicles could enhance the tumor cell invasion in vitro by transwell assay." (PMID 31705785, 2019). "In addition to the effects on tumor cell migration and invasion, we also assessed the effect of TPM3 knockdown on HCC cell growth." (PMID 20356415, 2010). "In addition, in our unpublished study, the combined use of TPM3 knockdown and chemotherapeutic agents have been more effective to reduce tumor cell viabilities than the use of chemotherapeutic agents only." (PMID 20356415, 2010). "Taken together, it could be suggested that reduced tumor cell growth in siTPM3 treated HCC cells might be due to TPM3 knockdown-related downregulation of Snail." (PMID 20356415, 2010). "In addition, CD34, EDIL3, and TPM3 were positively correlated with signaling pathways related to tumor immune response, invasion, and metastasis, particularly the IL6/JAK/STAT3, inflammatory response, TNF-α signaling via NF-kB, and epithelial-mesenchymal transition." (PMID 38840234, 2024). "The case of patient #8 (2 y/F), who had a TPM3::NTRK1-fused spinal HGG, highlights the potential efficacy of TRK inhibitor (larotrectinib) therapy in the management of recurrent and challenging tumours." (PMID 39014476, 2024). "Further bioinformatics analysis of miR-24-1-5p targets, including CD34, ACACA, TPM3, UFC1, EDIL3, and CHEK1, reinforces their role in tumor immune cell infiltration and the transformation of the tumor microenvironment." (PMID 38840234, 2024). "The inhibition of MALAT1 upregulated the expression of miR-1-3p via a ceRNA mechanism, which subsequently suppressed tumor cell metastasis and tumor angiogenesis by inactivating the downstream effectors Coronin-1C (CORO1C) and tropomyosin 3 (TPM3)." (PMID 38540273, 2024). "The analysis of the cfDNA NGS panel before treatment with larotrectinib revealed both TPM3::NTRK1 fusion and MDM2/CDK4 amplification, reliably reflecting the genetic alterations of the original pelvic tumor tissue." (PMID 36652666, 2023). "The tumor specimen was sent for further analysis for next-generation sequencing (NGS; ACTOnco+, ACT Genomics), which mainly disclosed TPM3::NTRK fusion (Appendix Fig A1), and MDM2/CDK4 gene amplification." (PMID 36652666, 2023). "Nine tumors harbored an NTRK1 fusion with different fusion partners (4 × TPM3, 4 × LMNA, 1 × SFPQ), one tumor harbored an ETV6::NTRK3 fusion." (PMID 37067589, 2023). "The most common tumour type with ETV6 was salivary gland (36.8%), with TPM3 was CRC (29.3%) and with LMNA was CRC (39.4%)." (PMID 34285332, 2021). "To investigate the distribution of Tpm3 throughout CRC progression, we stratified results based on the Union for International Cancer Control’s (UICC) TNM tumor classification stages." (PMID 31810358, 2019). "Among these, we found some tumor suppressor genes (e.g. H19, ACTN4) that were down-regulated and some genes related to tumor progression and metastasis formation (e.g. ENPP2, GRIA3, TPM3) that were up-regulated." (PMID 23049808, 2012).